MIR4773-2 (microRNA 4773-2)
Synonyms: hsa-mir-4773-2
Gene: MicroRNA gene on chromosome 2 (151,368,334 to 151,368,411, reverse strand). Ensembl gene ENSG00000283569.
Homologues: Orthologues: chimpanzee MIR4773-2 (100% identical).